DNMT3A (DNA methyltransferase 3 alpha)
Diseases named in the same sentence as DNMT3A in open-access papers (continued):
Sharing a sentence is not in itself a finding about the gene and the disease.
breast cancer (continued). "We believe that DNA hypermethylation of miR-133a-3p and the miR-133a-3p/MAML1/DNMT3A axis may provide novel therapeutic targets for the treatment of breast cancer, which is also of crucial significance for clinical prevention and diagnosis." (PMID 31660998, 2019). "Also, these compounds cause down-regulation of DNMT1, DNMT3a and DNMT3b in HCC1806 breast cancer cells." (PMID 30881375, 2019). "To explore which type of DNA methyltransferases could be affected by MAML1, we first analyzed the correlation between MAML1 and common DNA methyltransferases (DNMT1, DNMT3A/B) in 1085 breast cancer tissues from the GEPIA public database." (PMID 31660998, 2019). "DNMT3a and 3b expression levels varied among several breast cancer cell lines." (PMID 30940798, 2019). "Taken together, our findings revealed a novel miR-133a-3p/MAML1/DNMT3A positive feedback loop in breast cancer cells, which may become a potential therapeutic target for breast cancer." (PMID 31660998, 2019). "In breast carcinoma, chronic intermittent exposure to adriamycin induced hypermethylation that was associated with multidrug resistant phenotype in correlation to an upregulation of DNMT1, DNMT3A and DNMT3B and an increase in DNA methyltransferase activity." (PMID 31022903, 2019). "We began the study with evaluating MYC, DNMT3A and miR‐200b levels in breast cancer tissues." (PMID 30324719, 2018). "More recently, the focal adhesion protein Kindlin 2 was found to form a complex with DNA (cytosine-5-)-methyltransferase 3 alpha (DNMT3A) in breast cancer cells to induce CpG island hypermethylation of the miR-200 promoter, leading to the decreased expression of the miR-200 family members." (PMID 30542509, 2018). "It is possible that the noted DNMT3a downregulation could be an effector event of MTA1 overexpression during breast cancer progression." (PMID 28393842, 2017). "We found that increased levels of MTA1 correlate well with an elevated level of IGFBP3 as well as low DNMT3a and this may result in poor prognosis of breast cancer patients." (PMID 28393842, 2017). "Interestingly, low levels of DNMT3a correlates well with a high IGFBP3 expression and associate with a poor distant metastasis-free survival of breast cancer patients." (PMID 28393842, 2017). "The regulation of DNMT3a by MTA1 may be clinically relevant as low and high levels of DNMT3a and MTA1, respectively, may be associated with a poor survival of patients not only with breast cancer but also in other cancers." (PMID 28393842, 2017). "We speculate that ERα-activated-DNMT1 pathway dominantly propels the drug-induced global DNA hypermethylation in breast cancer, although the effects of DNMT3a/3b cannot be fully excluded in this experimental system and remains to be tested further." (PMID 26980709, 2016). "In addition, a more recent study demonstrated that natural compounds such as EGCG, genistein, withaferin A, curcumin, resveratrol, and guggulsterone inhibit DNMT1, DNMT3a, and DNMT3b expression in breast cancer cell lines." (PMID 24822169, 2014). "In addition, we summarize how DNMT3A and DNMT3B are regulated by non-coding RNAs and signaling pathways in breast cancer, and targeting the expression levels of DNMT3A and DNMT3B may be a promising therapeutic approach for breast cancer." (PMID 35620052, 2022). "At the same time, scientific studies have shown interference in DNA methyltransferase (DNMT) activity, in particular DNMT1 and DNMT3a, which have been reduced in breast cancer cells treated with SFN, suggesting that this compound may be able to repress hTERT through specific epigenetic pathways." (PMID 36235389, 2022). "Therefore, the miR-133a-3p/MAML1/DNMT3A positive feedback axis might provide potential targets for breast cancer therapy." (PMID 31660998, 2019). "In addition to DNMT1, DNMT3A was also found to be elevated in sporadic breast cancer." (PMID 27525019, 2016). "Interestingly, DNMT1 and DNMT3a were overexpressed in only 5 and 3% of breast carcinomas." (PMID 24822169, 2014).
breast cancer (continued). "DNA methylation is facilitated by DNA methyltransferases (DNMTs) such as DNMT1, DNMT3A, and DNMT3B, all of which are overexpressed in breast cancer patients with advanced clinical disease stages." (PMID 40427627, 2025). "We further explored the involvement of DNMT3A in hypoxia-induced EMT process of two other types of cancer cells, namely the breast cancer cell line MCF-7 and hepatocellular carcinoma cell line Hep G2." (PMID 40764968, 2025). "All survival data for survival analysis were collected for breast cancer patients, available at cbioportal.org, with protein expression data for GMPS and DNMT3A." (PMID 41465346, 2025). "Taken together, our findings suggest that DNMT3A activates the EGFR-MEK-ERK signaling pathway by silencing ADAMTS8 transcription through methylation, thereby promoting breast cancer development." (PMID 40323963, 2025). "Therefore, DNMT3A may serve as an inhibitory target in breast cancer-targeted therapy." (PMID 40323963, 2025). "Increased expression of DNMT1, DNMT3A, and DNMT3B was found in various cancers such as breast cancer, pancreatic cancer, lung cancer, hematological malignancies, and head and neck squamous cell carcinoma." (PMID 40507223, 2025). "We found that, compared with normal tissues, the protein levels of DNMT3A and DNMT3B in breast cancer tissues were increased, and the protein level of TAT was decreased." (PMID 39334853, 2024). "Our study observed that the high level expressed SND1 in TNBC cell lines significantly increased the expression of DNMT3A, leading to aberrant methylation patterns of CDH1 and promoting breast cancer metastasis." (PMID 37885030, 2023). "Here we found that DNMT3a-mediated DPT, promoter hypermethylation results in the downregulation of DPT expression in breast cancer and its low expression correlated with poor prognosis." (PMID 36774339, 2023). "Studies have shown that DNMT1, DNMT3A and DNMT3B are usually highly expressed in patients with advanced breast cancer." (PMID 37298314, 2023). "For example, lncRNA 01638 downregulation repressed the expression of DNMT1, DNMT3A and DNMT3B, and increased the expression of PTEN and BRCA1, resulting in inhibition of proliferation and invasion in HER2-positive breast cancer cells." (PMID 35620052, 2022). "LncRNA MALAT1 increased the expression of DNMT1, DNMT3A and DNMT3B and inhibited the BRCA1 and PTEN expression, leading to regulating of herceptin sensitivity in HER2-positive breast cancer." (PMID 35620052, 2022). "For example, the upregulation of DNMTs, such as DNMT1, DNMT3A, and DNMT3B, is correlated with endocrine therapy resistance in ER+ breast cancer." (PMID 35453496, 2022). "In conclusion, DNMT3A and DNMT3B play an enormously critical role in the occurrence and development of breast cancer." (PMID 35620052, 2022). "Expression of NSUN1, NSUN2, NSUN5, DNMT1, DNMT3A, DNMT3B, and ALYREF was significantly increased, but DNMT2 and TET2 expression was markedly decreased in breast cancer tissues when compared with normal breast tissues." (PMID 35812757, 2022). "Among KEGG methionine metabolism genes, we have revealed five poor prognostic markers, including AHCY, CBS, DNMT3A, and MTAP, for neuroblastoma and breast cancer patients." (PMID 36361596, 2022). "In HCC1806 breast cancer cells, resveratrol downregulates the DNMT1, DNMT3a, DNMT3b, and negatively regulated hTERT with the inhibition of SIRT followed by the inhibition of breast cancer cell growth." (PMID 36235389, 2022). "Demethylation agent 5-aza-dc, an inhibitor of DNMT3A and DNMT3B, increased the expression of caspase 8 and maspin in breast cancer cell lines." (PMID 35620052, 2022). "Similar to DNMT3A/B, TET2 is a potential biomarker for ER+ breast cancer progression and metastasis." (PMID 35453496, 2022). "FEN1-mediated DNMT3a up-regulation, released the suppression of its targeting MET and EGFR, and promoted breast cancer cell proliferation by activating PI3K/AKT and MAPK/ERK pathways in MCF-7cells." (PMID 35620052, 2022).
breast cancer (continued). "Another group showed that microRNA-29b (miR-29b) can bind with 3′-UTR of DNMT3A and DNMT3B and inhibit the mRNA level of DNMT3A and DNMT3B, leading to multiple gene promoter methylation in breast cancer cells and suppression of cell proliferation." (PMID 35620052, 2022). "One study identified 16 SNPs in DNMTs, including 5 SNPs in DNMT1, 6 SNPs in DNMT3A, 3 SNPs in DNMT3B, 1 SNP in DNMT3L and 1 SNP in DNMT2 in 408 breast cancer patients and 469 controls." (PMID 35620052, 2022). "Recently, piR-823 increased the expression of DNMTs, including DNMT1, DNMT3A and DNMT3B, enhanced APC DNA methylation and subsequently activated Wnt pathway, leading to induction of CSCs in luminal breast cancer." (PMID 35620052, 2022). "Four genes (AHCY, CBS, DNMT3A, and MTAP) from the methionine metabolism gene set are markers of poor prognosis for neuroblastoma and breast cancer patients." (PMID 36361596, 2022). "Another group indicated that higher expression of DNMT3A was observed in Grade III group and larger tumors in breast cancer patients." (PMID 35620052, 2022). "This review will provide reference for further studies on the biological functions and molecular mechanisms of DNMT3A and DNMT3B in breast cancer." (PMID 35620052, 2022). "The expression of miR-29a and miR-29b were found to target DNMT3A and DNMT3B in in vitro and in vivo models of breast cancer." (PMID 33604794, 2021). "In another study, the expression of DNMT1, DNMT3A, and DNMT3B in 256 breast cancer and 36 breast fibroadenoma cases were investigated." (PMID 33498667, 2021). "Approximately, 30% of breast cancer patients showed overexpression of DNMT3B and 3–5% showed overexpression of DNMT1 and DNMT3A." (PMID 33604794, 2021). "To establish the potential roles of the various DNMTs in mediating FOXO3a promoter methylation in breast cancer, we knocked down DNMT1, DNMT3A, and DNMT3B in breast cancer cells using specific small interfering RNAs (siRNAs)." (PMID 31296961, 2020). "According to the published literature, DNMT3A can mediate PTEN and BRCA1 promotor hypermethylation and decrease the expression of PTEN and BRCA1 in several cancers, including breast cancer." (PMID 32756009, 2020). "It is noted that DNMT1, DNMT3a, and DNMT3b are all recruited to the FOXO3 promoter in breast cancer HCC70 and MDA-MB-468 cells." (PMID 31296961, 2020). "Another study demonstrated that FEN1 promoted breast cancer cell proliferation via an epigenetic mechanism whereby FEN1-mediated up-regulation of DNMT1 and DNMT3a." (PMID 31534853, 2019). "2We found that once DNMT3a was efficiently knocked down, the mRNA level of HIF-1alpha increased in non-invasive MCF-7 breast cancer cells." (PMID 30940798, 2019). "The RNA‐sequencing data of TCGA showed DNMT3A and MYC were highly expressed in TNBC tissues compared with in other breast cancer subtypes." (PMID 30324719, 2018). "In brief, findings presented here identified an upstream regulatory role of MTA1 coregulator in controlling the expression of DNMT3a and IGFBP3 in cancer cells and possibly modifying the biology of breast cancer progression." (PMID 28393842, 2017). "Together findings presented here recognize an inherent role of MTA1 as a modifier of DNMT3a and IGFBP3 expression, and consequently, the role of MTA1-DNMT3a-IGFBP3 axis in breast cancer progression." (PMID 28393842, 2017). "However, the expression of DNMT3a in breast cancer remains unclear." (PMID 28393842, 2017). "Regarding the importance of DNMT3b, several studies demonstrated that DNMT3b is overexpressed at higher frequency than DNMT3a and DNMT1 in CRC and breast cancer 27–29." (PMID 28090275, 2017). "We first searched for possible correlations between MTA1, DNMT3a, and IGFBP3 using eight breast cancer datasets." (PMID 28393842, 2017). "We report greater efficacy of these compounds in combination with regard to breast cancer cell death and down-regulation of overexpressed HDAC1, DNMT3A and DNMT3B." (PMID 28534825, 2017).
breast cancer (continued). "We found that the levels of MTA1 and DNMT3a are inversely correlate in human cancer at-large, and that low DNMT3a in combination of high MTA1 expression predicts a poor clinical outcome in breast cancer patients." (PMID 28393842, 2017). "To further analyze DNMTs and HDACs we assessed key epigenetic modifiers, DNMT1, DNMT3A, DNMT3B and HDAC1, and found decreases at both the mRNA and protein levels in one or both breast cancer cell lines." (PMID 28534825, 2017). "To experimentally validate the noticed, presumed negative regulation of DNMT3a expression by MTA1, we selected breast cancer model system for subsequent studies." (PMID 28393842, 2017). "We found that MTA1 overexpression results in a marked reduction in the level of DNMT3a, while MTA1 silencing leads to an increased DNMT3a expression in breast cancer MCF-7 and SKBR-3 cells." (PMID 28393842, 2017). "Similar to breast cancer cells, MTA1 silencing or overexpression in HCT116 colon cancer cells also leads to upregulation or downregulation of DNMT3a, respectively." (PMID 28393842, 2017). "To eliminate the possible effect of endogenous DNMT3A protein, we tested a series of solid tumor cell lines and found little DNMT3A expression in MDA-MB-231, a breast cancer cell line." (PMID 27724883, 2016). "Demethylation agent 5-aza-2'-deoxycytidine (5-aza-dc) selectively inhibits DNA methyltransferases, DNMT3a and DNMT3b, and restored CASP8 and maspin gene expression in breast cancer cells." (PMID 20132554, 2010). "Finally, in interesting parallel, knockdown of DNMT3A also would prevent hypoxia-induced EMT, transcriptional activation of TWIST1 gene, and global genomic 5mC demethylation in the breast cancer cells (MCF-7) and the hepatocellular carcinoma cells (Hep G2)." (PMID 40764968, 2025). "MiR-133a-3p is epigenetically suppressed and silenced by promoter methylation, which leads to a significant increase in the proliferation, migration, invasion and stemness of breast cancer cells in vitro, mainly through the miR-133a-3p/MAML1/DNMT3A positive feedback loop." (PMID 37298314, 2023). "Apple polyphenol extracts inhibited the proliferation and migration of human breast cancer MDA‐MB‐231 cells by reducing the expression of ubiquitin like with PHD and ring finger domains 1 (UHRF1), matrix metalloproteinase 2 (MMP2), DNA methyltransferase 3 alpha (DNMT3a), and DNMT3b." (PMID 37701204, 2023). "Moreover, DNMT3A expression has been correlated with shorter DFS and OS times in breast cancer patients." (PMID 37885030, 2023). "This study suggested that miR-29b could regulate DNMT3A and DNMT3B and suppress proliferation of breast cancer cells." (PMID 35620052, 2022). "Clearly, numerous miRNAs regulate the expression of DNMT3A and DNMT3B in breast cancer." (PMID 35620052, 2022). "The negative correlation between miR-101 and DNMT3A expression has been confirmed in breast cancer, lung cancer, brain glioma, and other tumors." (PMID 36497343, 2022). "Another group clarified that miR-143 decreased the expression of DNMT3A at mRNA and protein levels, and subsequently decreased the PTEN hypermethylation and enhanced TNFRSF10C methylation, leading to suppression of proliferation of breast cancer cells." (PMID 35620052, 2022). "We also highlighted that targeting DNMT3A and DNMT3B could be useful for anti-breast cancer treatment." (PMID 35620052, 2022). "Similarly, overexpression of miR-29b-1-5p repressed the expression of DNMT1, DNMT3A and DNMT3B and elevated the expression of RASSF1A, CCND2 and HIN1 in breast cancer cells." (PMID 35620052, 2022). "Moreover, miR-203 and miR-150 can regulate the expression of DNMT3A and DNMT3B in breast cancer cells, resulting in regulation of CD44, ALDH1A3, OCT3/4, SOX2 expression, which are critical for breast cancer stem cell development." (PMID 35620052, 2022). "DNMT1, DNMT3A and DNMT3B increased the DNA methylation of FOXF2 in breast cancer cells." (PMID 35620052, 2022).
breast cancer (continued). "Moreover, combined treatments with SFN and withaferin A promoted cell death in breast cancer cells through the inhibition of DNMT1, DNMT3a, and HDAC activities in MCF-7 cells." (PMID 30881375, 2019). "The IHC analysis showed that MYC and DNMT3A were up‐regulated in TNBC tissues than other breast cancer subtypes (H‐score of MYC, ER+, 148.0 ± 12.2; HER2+, 145.2 ± 15.3; TNBC, 182.5 ± 8.3; H‐score of DNMT3A, ER+, 127.3 ± 9.3; HER2+, 150.5 ± 14.6; TNBC, 160.6 ± 7.9)." (PMID 30324719, 2018). "In addition, MTA1 overexpression correlates well with low levels of DNMT3a which, in turn also correlates with a high IGFBP3 status in breast cancer patients and predicts a poor clinical outcome for breast cancer patients." (PMID 28393842, 2017). "In this study we aimed to investigate the impact of combinatorial SFN and WA on MCF-7 estrogen receptor-positive (ER (+)) and MDA-MB-231 ER (−) breast cancer cell proliferation in conjunction with their role in the epigenetic gene expression of DNMT1, DNMT3A, DNMT3B and HDAC1." (PMID 28534825, 2017). "Five genomic loci corresponded to the criteria mentioned, and were further analyzed in the group of female Caucasian breast cancer patients and controls: DNMT1 SNP (A201G, rs2228612), DNMT3A SNPs (G301C, rs34843713 and G301A, rs34191084) and DNMT3B SNPs (C501T, rs406193 and G301A, rs35846833)." (PMID 23638630, 2013). "Panobinostat was shown to downregulate DNMT1 without affecting DNMT3a and 3b in human breast cancer cells and human acute leukemia cells while we observed an additional effect on DNMT3a in the used HCC cell lines." (PMID 22943463, 2012). "DNA methyltransferases (DNMTs), especially DNMT1 and DNMT3a, were also decreased in SFN-treated breast cancer cells suggesting that SFN may repress hTERT by impacting epigenetic pathways." (PMID 20625516, 2010). "However, it did inhibit DNMT3a and DNMT3b in MDAMB231 and BT474 (ER positive and HER2 positive) breast cancer cells." (PMID 20132554, 2010). "FEN1 was reported to elevate the expression of DNMT3A and promote their interaction among FEN1/PCNA/DNMT3A and suppressed the expression of miR-200a-5p, leading to upregulation of miR-200a-5p targets, MET and EGFR, which contribute to enhancement of growth of breast cancer cells." (PMID 35620052, 2022). "Moreover, DNMT3A was correlated with a shorter DFS and OS in breast cancer patients." (PMID 35620052, 2022). "Taken together, these results suggest that DNMT3a may be the primary protein responsible for methylation of CpG and non-CpGs sites in the HIF-1α gene promoter around TSS and, thus, suppresses HIF-1α expression in luminal breast cancer." (PMID 30940798, 2019). "Collectively, these findings suggest that CpG and non-CpG methylation within the HIF-1α gene promoter and first exon may play key roles in HIF-1α expression in breast cancer, and that this methylation at CpG and non-CpG sites is regulated by DNMT3a." (PMID 30940798, 2019). "However, a detailed mechanistic study will be needed to understand the absence of hypermethylation in breast cancer cells in relation with DNMT3A or DNMT3B levels and other molecular heterogeneity." (PMID 31068808, 2019). "Here, we showed that compression induces miR-9 downregulation via DNMT3A-dependent promoter methylation, which leads to the upregulation of miR-9 target genes (LAMC2, ITGA6, and EIF4E) thus potentiating signal transduction for VEGFA expression in CAFs and breast cancer cells." (PMID 28252641, 2017). "Furthermore, while knockdown of either UHRF1 or UHRF2 led to increased DNMT3A, a more pronounced increase of DNMT3A was observed when both UHRF1 and UHRF2 were knocked down in the MDA-231 breast cancer cell line, indicating that UHRF1 and UHRF2 cooperatively regulate DNMT3A." (PMID 27462454, 2016).